RN7SL154P (RNA, 7SL, cytoplasmic 154, pseudogene)
Gene: Miscellaneous RNA gene on chromosome 19 (34,421,988 to 34,422,311, reverse strand). Ensembl gene ENSG00000264317.
Homologues: Orthologues: chimpanzee Metazoa_SRP (93% identical), macaque Metazoa_SRP (38% identical). Paralogues in human: Metazoa_SRP (75% identical), RN7SL134P (75% identical), RN7SL784P (74% identical), RN7SL123P (73% identical), RN7SL774P (73% identical), RN7SL474P (73% identical), RN7SL811P (73% identical), Metazoa_SRP (71% identical), RN7SL96P (71% identical), RN7SL339P (70% identical), RN7SL163P (69% identical), RN7SL488P (69% identical), and 707 more.